HSD17B12 (hydroxysteroid 17-beta dehydrogenase 12)
Diseases named in the same sentence as HSD17B12 in open-access papers (continued):
Sharing a sentence is not in itself a finding about the gene and the disease.
tumor (8 papers, 2010 to 2026). "The expression of HSD17B12 was associated with the metastatic phenotype in tumor cell lines, through its function in Arachinoid Acid (AA) metabolism, linking the metabolism of eicosanoids and cytoskeleton remodeling." (PMID 25945082, 2015). "Moreover, exosomal PD-L1 (exoPD-L1), which exhibits robust and persistent suppression effects of the anti-tumor immune response, was significantly elevated in HSD17B12-deficient RKO cells." (PMID 41592073, 2026). "The observed correlation underscores HSD17B12’s potential role in enhancing anti-tumor immune responses." (PMID 41592073, 2026). "This study identifies the metabolic enzyme HSD17B12 as a regulator of PD-L1 degradation and shows that an HSD17B12-derived peptide boosts anti-tumor immunity in a mouse model." (PMID 41592073, 2026). "In ovarian cancer, HSD17B12 silencing significantly inhibited tumor cell proliferation, while exogenous arachidonic acid restored the growth inhibitory effect, suggesting its function depends on the reductase activity." (PMID 41592073, 2026). "In this study, we demonstrate that HSD17B12 enhances anti-tumor immunity and represents a promising therapeutic target." (PMID 41592073, 2026). "Our analysis revealed that HSD17B12 expression was significantly elevated in CRC tumor tissue, and this upregulation was associated with a favorable prognosis." (PMID 41592073, 2026). "Mechanistically, HSD17B12 boosts anti-tumor immunity by facilitating VAC14-ESCRT-mediated degradation of PD-L1, independently of CMTM6, HIP1R, and palmitoylation." (PMID 41592073, 2026). "In contrast, the HSD17B12 enzyme showed higher methylation in normal tissue samples compared to tumour tissue." (PMID 36674737, 2023). "In women with ER+/PR+ tumor, HSD17B12 transcript amount (r = 0.58; P = .0479) was correlated with relative E1 amount in breast adipose tissue." (PMID 31853538, 2020). "Moreover, HSD17B12 was highly expressed in tumour tissues compared with the adjacent normal tissues from the databases." (PMID 33118286, 2020). "To explore the effect of rs10838164 on HSD17B12 expression, we conducted eQTL analysis and found that the rs10838164 C>T could significantly increase the expression levels of HSD17B12 in tumours (P = 1.78 × 10−11)." (PMID 33118286, 2020). "Additionally, in all cases, Sequenom methylation values were significantly associated with respective covariates; tumor stage with FES methylation (P = 0.05), tumor size with P2RX7 (P<0.005) and HSD17B12 methylation (P<0.02), and tumor grade with GSTM2 methylation (P<0.001)." (PMID 20686660, 2010). "Among dMMR CRC patients who were pathologically classified as tumor regression grade 2 (TRG2) after immunotherapy, HSD17B12 expression was significantly lower compared to the broader nonimmunotherapy CRC cohort." (PMID 41592073, 2026). "Although HSD17B12 has long been known for its function in fatty acid elongation, its function and mechanism in tumor immunity have not been explored." (PMID 41592073, 2026). "Our study found that the very-long-chain 3-oxoacyl-CoA reductase, HSD17B12, regulates tumor immunity regardless of its reductase activity." (PMID 41592073, 2026).
HSD17B12 also shares sentences with these, for which no sentence is quoted: cardiovascular disease (1 paper); colorectal tumour (1); coronary artery diseases (1); embryonal carcinoma (1); essential thrombocythemia (1); geographic atrophy (1); Hepatic fibrosis (1); hepatoma (1); Hypertension (1); infection (1); ischemic stroke (1); lipodystrophy (1); metabolic disease (1); neurological disorders (1); oral cancer (1); schizophrenia (1); seminoma (1); Stroke (1); triple-negative breast carcinoma (1); yolk sac tumor (1).